CRP (C-reactive protein)
Diseases named in the same sentence as CRP in open-access papers (continued):
Sharing a sentence is not in itself a finding about the gene and the disease.
liver fibrosis (65 papers, 2011 to 2026). "This study aimed to investigate the association between high-sensitivity C-reactive protein (hsCRP) levels and hepatic fibrosis in patients with metabolic dysfunction-associated steatotic liver disease (MASLD) and assess its predictive efficacy." (PMID 39995674, 2025). "Significant associations were observed between inflammatory markers (CRP, p = 0.016 and fecal calprotectin, p = 0.022) and hepatic fibrosis." (PMID 41226329, 2025). "We will conduct further prospective studies, collecting CRP and other factors in the future, further uncover the association between CRP and significant liver fibrosis in CHB patients." (PMID 34858162, 2021). "Including IFNL genotype and inflammatory markers IL-8, sICAM-1, RANTES, hs-CRP, and sCD14 enabled better prediction of the 3-year risk of significant liver fibrosis over clinical predictors alone." (PMID 28467457, 2017). "Importantly, systemic inflammation, as reflected by CRP levels, partially mediated this relationship, suggesting a mechanistic link between poor nutritional status and progression of hepatic fibrosis in this high-risk population." (PMID 41463388, 2025). "Also HBV induced liver fibrosis was associated with elevated levels of CRP similar to the current findings in HCV infection." (PMID 27135246, 2016). "The high-sensitivity CRP/high-density lipoprotein cholesterol (hs-CRP/HDL-C) index was shown to correlate positively with both metabolic dysfunction-associated steatotic liver disease (MASLD) and advanced liver fibrosis." (PMID 40869686, 2025). "This study sought to examine the association between hs-CRP levels and the risk of metabolic dysfunction-associated steatotic liver disease (MASLD) and liver fibrosis (LF)." (PMID 40938077, 2025). "Significant differences were found in platelet count, liver enzymes (ALT, AST, GGTP, ALP), inflammatory markers (CRP, IL-6, IL-18), fibrinogen, and markers of liver fibrosis (APRI, FIB-4, ElastPQ)." (PMID 40806277, 2025). "In a 12-wk trial, a low-free sugar diet significantly reduced hepatic fibrosis, CRP, and TNF-α in MASLD." (PMID 39842721, 2025). "Further research found that the increased CRP, IL-1β, and TNF-α were significantly associated with MASH and hepatic fibrosis." (PMID 39605886, 2024). "GH therapy replacement has already shown improvement in the levels of hepatic fibrosis, probably because of the reduction in the levels of CRP and significant decrease in the total amount of hepatic hyaluronic acid and Type IV collagen." (PMID 36831184, 2023). "We found significant associations for CRP with NASH (OR, 1.60; 95% CI, 1.17‐2.19; P=0.003) and hepatic fibrosis (OR, 1.18; 95% CI, 1.06‐1.32; P=0.003), which were consistent with overall effect." (PMID 35603224, 2022). "For different subtypes of NAFLD, we found significant associations of CRP, IL-1β, and TNF-α with NASH and hepatic fibrosis." (PMID 35603224, 2022). "The role of platelet-derived growth factor A (PDGF-A) in the formation of liver fibrosis in vivo can be evaluated in transgenic mice with hepatocellular specific overexpression of PDGF-A by the C-reactive protein (CRP) gene promoter." (PMID 34122138, 2021). "As well-established in liver fibrosis we show that CRP, a surrogate parameter for inflammation, correlates with the CP score in our large cohort of patients with liver fibrosis." (PMID 33746950, 2021). "Genes encoding IL6, CRP and NOS2 were previously reported to exhibit dysregulation in liver fibrosis." (PMID 27135246, 2016). "One approach utilizes the testing of biochemical markers of liver fibrosis: hyaluronic acid, adiponectin, high-sensitivity CRP, type IV collagen, serum IL-6, leptin, laminin, c-peptide, and cytokeratin-18." (PMID 23555578, 2013). "Several studies have reported that cigarette smoking accelerates the progression of liver fibrosis in patients with chronic hepatitis C, and typical inflammatory biomarkers such as CRP and fibrinogen are elevated in smokers." (PMID 24324779, 2013).
liver fibrosis (continued). "The positive correlation between ferritin and liver stiffness, along with higher CRP levels in the fibrosis group -even within the normal range- suggests that ongoing low-grade inflammation may contribute to the development of liver fibrosis." (PMID 41507929, 2026). "Reduced glutathione may also play a role in modulating the immune response by lowering levels of inflammatory markers such as TNF-α, CRP, and IL-6, which are known to contribute to liver fibrosis and inflammation." (PMID 41281287, 2025). "In addition, we found that liver fibrosis is the most significant risk factor for all-cause mortality in patients with MASLD, and that high CRP concentration is the most significant risk factor for all-cause mortality in those with NAFLD." (PMID 41171731, 2025). "In addition, 112 cases had missing data for non-invasive liver fibrosis assessment, and 64 individuals with missing insulin or CRP measurements were excluded, leading to the final sample of 10985 participants." (PMID 40642596, 2025). "However, a significant research gap persists regarding the association between hs-CRP, MASLD, and liver fibrosis (LF)." (PMID 40938077, 2025). "However, studies have shown that the NLR is superior to CRP in predicting the occurrence of liver fibrosis and differentiated thyroid cancer." (PMID 37724554, 2023). "But microbial therapies could not ameliorate body mass index (BMI), energy, carbohydrate, fat intake, fasting blood sugar, HbA1c, insulin, high-sensitivity C-reactive protein (hs-CRP), and hepatic fibrosis of patients with NAFLD." (PMID 36386939, 2022). "Both CRP and IL-37 serum levels correlate with Child Pugh (CP) score and are significantly lower in healthy controls than in patients with different extent of liver fibrosis as indicated by Child-Pugh-score." (PMID 33746950, 2021). "C-reactive protein is considered associated with HBV replication, liver related damage, and fibrosis, and serum CRP may be a marker for the diagnosis of liver fibrosis in patients with HBV." (PMID 30971239, 2019). "Serum LBP was shown to associate with hs-CRP, NALFD, and NAFLD with liver fibrosis." (PMID 30458048, 2018). "Since the classic short pentraxin CRP is produced in the liver, it is thought that CRP levels in NAFLD may be a more sensitive marker for predicting severity of liver fibrosis when compared to PTX3 levels." (PMID 26997950, 2016). "Moreover, we found that CRP and Hp were both lower in liver fibrosis of TAA-induced rats and clinical hepatitis C virus-infected patients." (PMID 21806828, 2011). "Interestingly, we observed that CRP and Hp were both downregulated in the serum of liver fibrosis rats compared to normal, AFL, and NAFL rats (all p < 0.05)." (PMID 21806828, 2011). "Also, there was a significant difference in hs-CRP among liver fibrosis stages (p = 0.023)." (PMID 37029427, 2023). "While AST and CRP did not have a significant value in the multivariate analysis, they were still strongly associated in the univariate analysis, with important degrees of liver fibrosis." (PMID 35453849, 2022). "Some researchers proposed that this elevated interleukin-6, which is partly secreted by activated macrophages induced during liver fibrosis, might induce inflammatory response proteins in the hepatocytes (such as CRP (C-reactive protein), ferritin, complement, and clotting factors)." (PMID 35369116, 2022). "Hepatic fibrosis/hepatic stellate cell activation was also associated with adiponectin concentrations at week 4, whereas the LXR/retinoid-X-receptor (RXR) and FXR/RXR activation pathway were associated with cortisol at baseline correlating with CRP, SAP A, and sIL-2Rα." (PMID 28674532, 2017). "Moreover, in order to evaluate the decreased expressions of CRP and Hp in the serum of liver fibrosis rats, we measured serum CRP and Hp concentrations in clinical patients with non-alcoholic steatohepatitis (NASH) and HCV-induced liver fibrosis compared to healthy controls." (PMID 21806828, 2011).
liver fibrosis (continued). "Fibrosis-5 (FIB-5) index is a marker of liver fibrosis and has been shown to have a good prognostic value for patients with acute heart failure (AHF), and C-reactive protein (CRP) has inflammatory properties and predicts adverse prognosis in patients with HF." (PMID 37794360, 2023). "Serum CRP levels are predictive of NAFLD and have been related to the presence and severity of liver fibrosis." (PMID 33665176, 2021). "We suggest that CRP is suitable to serve as a candidate biomarker of AFL, and Hp is a reliable biomarker that decrease in NASH and liver fibrosis." (PMID 21806828, 2011). "Furthermore, serum CRP levels are predictive of NAFLD and have been related to the presence and severity of liver fibrosis." (PMID 36894963, 2023). "Our results also showed that CRP, IL-1β, and TNF-α were significantly associated with non-alcoholic steatohepatitis (NASH) and hepatic fibrosis." (PMID 35603224, 2022). "Liver enzymes, noninvasive liver fibrosis scores and liver function tests showed additive effects across metHC, AUD and metAUD compared to HC, with the largest effects in metAUD for GGT, AST, ALT, CRP, albumin, direct bilirubin, FIB-4, LiverRisk and NFS (p < 0.001)." (PMID 41780539, 2026).
multiple myeloma (65 papers, 2004 to 2026). "Third, the Myeloma Research Alliance Risk Profile has also been developed for prognostication of transplant-ineligible myeloma patients; this risk score also included CRP level together with WHO performance status and the International Staging System." (PMID 32707721, 2020). "In subjects with latent MM who were at risk of evolution to active myeloma, therapy with IL-1 inhibitors reduced the myeloma growth and CRP concentrations in those who responded, with a chronic disease state and an improved PFS." (PMID 29089667, 2017). "In addition to compression fractures, hematologic diseases such as malignant lymphoma and myeloma were considered as causes of fever and CRP level elevation." (PMID 30945040, 2019). "Several previous studies demonstrated that CRP was associated with cell proliferation and apoptosis in endothelial cells, endothelial progenitor cells, renal tubular epithelial cells, and myeloma cells, but this is the first study to investigate the effect of CRP on ADSC proliferation and apoptosis." (PMID 27526687, 2016). "In addition to the prognostic value of baseline biological markers including high levels of β2-microglobulin (B2-M), lactate dehydrogenase (LDH), and serum albumin, elevations of serum C-reactive protein (CRP) have been consistently associated with a poor prognosis in myeloma." (PMID 16969356, 2006). "This study identified five key predictors of infection in multiple myeloma patients with MM: C-reactive protein, fasting blood glucose, lactate dehydrogenase, Eastern Cooperative Oncology Group (ECOG) score, and bone marrow plasma cell percentage." (PMID 41551150, 2025). "RDW correlates with elevated acute inflammatory markers like ESR, CRP, and interleukin-6, and is a biomarker in conditions like kidney disease and multiple myelomas." (PMID 41466195, 2025). "In the context of CAR T-cell therapy for multiple myeloma, recent research has elucidated the prognostic significance of inflammatory markers, particularly C-reactive protein, ferritin, and interleukin-6." (PMID 39286245, 2024). "ESR and plasma viscosity have demonstrated value as rule-in tests previously; level CRP itself was considered as a parameter with limited value for myeloma diagnosis and monitoring." (PMID 36835883, 2023). "It has been reported in the literature that CRP NMAs showed interference by monoclonal immunoglobulin, as well as by monoclonal IgM-κ, in a case with myeloma [1180,1181]." (PMID 37873776, 2023). "On the contrary, individuals at high CRP concentration were at decreased risks for multiple myeloma and CLL (FDR-adjusted Ptrend < 0.05)." (PMID 36117174, 2022). "It was found that IL-1Ra bound to the myeloma proliferative cells and decreased the level of C-reactive protein (CRP), a surrogate for IL-6 production." (PMID 35011853, 2021). "The percentage represents the quantity of anaemic patients investigated for vitamin B12, folate, ferritin, serum iron levels, CRP and myeloma screen (n=166)." (PMID 34155456, 2021). "Six (4%) of all anaemic patients had complete investigations including C-reactive protein (CRP) and myeloma screen." (PMID 34155456, 2021). "It has been reported that CRP-induced cytokine expression is also regulated by TWIST transcriptionally in myeloma cells." (PMID 32508836, 2020). "The results of previous studies suggest that in myeloma CRP concentration is dependent on IL-6 activity and indirectly reflects the state of bone marrow microenvironment." (PMID 29844872, 2018). "Observational studies have shown higher LDH, ALP, CRP, and IL-6 levels with extensive liver involvement in patients with multiple myeloma." (PMID 26221143, 2015). "CRP activated Akt, pERK, and NF-κB signaling pathways in these cells, led to increased IL-6 synthesis, and protected the myeloma cells from chemotherapy-induced apoptosis." (PMID 24167754, 2013). "These investigators found that primary myeloma cells and stressed myeloma cell lines bound CRP through FcγRIIA and FcγRIIC." (PMID 24167754, 2013).
multiple myeloma (continued). "Our results extend previous observations regarding the role of CRP as an independent prognostic marker in multiple myeloma, indicating that CRP has predictive power for patients with myeloma beyond the time of diagnosis." (PMID 16969356, 2006). "Of 71 surgically treated patients with myeloma bone disease, evaluated for CRP elevation prior to surgery, 26 (36.6%) were assigned to the negative group and 45 (63.4%) to the positive group." (PMID 16969356, 2006). "The major finding of this investigation is the inferior survival of patients with myeloma bone disease in whom CRP was elevated prior to surgery." (PMID 16969356, 2006). "In addition, C-reactive protein (CRP) significantly upregulated in serum of patients with multiple myeloma compared with healthy controls." (PMID 35342422, 2022). "Notably, inhibiting CRP expression by targeting IL-1 can prolong overall survival time for patients with multiple myeloma." (PMID 33013829, 2020). "Over‐expressed CRP involves various tumors, including lung, lymphoma, ovary, and multiple myeloma." (PMID 33201589, 2020). "CRP should generally be the first-line test, with the possible exception of myeloma." (PMID 31208975, 2019). "In contrast, CRP may protect myeloma cells from dexamethasone and melphalan-induced apoptosis in vitro and in vivo." (PMID 27129167, 2016). "Moreover, CRP was shown to directly enhance tumor cell proliferation under stressed conditions in a recent study on myeloma." (PMID 27733196, 2016). "We excluded 31 subjects who had either infection (under treatment for mycobacterium tuberculosis, n = 3), malignancy (lung, colon, prostate, tonsill cancer, multiple myeloma or malignant lymphoma; n = 6) or elevated serum CRP levels (>0.5 mg/dl, n = 26), with some overlaps." (PMID 26161663, 2015). "Thus, preoperative elevated CRP serum levels should be considered as an independent predictor of prognosis beyond diagnosis and might provide additional prognostic information for the risk stratification before surgical treatment in patients with myeloma bone disease." (PMID 16969356, 2006). "However, CRP may also act directly on myeloma cells to promote their proliferation under stress, leading to further weakening immune function and increasing infection risk." (PMID 41551150, 2025). "We analyzed a variety of clinical factors (gender, age, β2-MG, type of light chain, ISS stage, plasma cell number in bone marrow, peak concentration of IL-6 and CRP, and minimum value of CD4/CD8) that may be associated with CRS in patients with multiple myeloma separately." (PMID 33708205, 2021). "Finally, CRP may also be used as a biomarker for response to new, targeted therapy, in multiple myeloma." (PMID 32707721, 2020). "Furthermore, CRP targets to the p38/MAPK pathway causing lytic bone lesions and activates the PI3K/AKT/mTOR and the ERK/NF-κB pathway thereby inhibiting tumor cell apoptosis via the Fcγ receptor II in multiple myeloma." (PMID 33013829, 2020). "Moreover, we correlated them with markers of myeloma activity, such as serum levels of IL-6, IL-10, IL-15, beta-2 microglobulin (B2M), and C-reactive protein (CRP), as well as with plasma cells' infiltration and Ki-67-PI in the bone marrow, both in diagnosis and after effective therapy." (PMID 23936794, 2013). "In addition, CRP has a biological role in IL-6 production and chemoresistance in multiple myeloma." (PMID 20808314, 2010). "Taken together, these findings suggest that in patients with multiple myeloma, serum levels of CRP increase during disease activity and might be significantly correlated with specific disease characteristics including adverse prognostic features such as osteolyses in long weight bearing bones." (PMID 16969356, 2006). "Specifically for myeloma, previous research has shown that PV and ESR are more useful for diagnosis than CRP." (PMID 36765931, 2023).